ATP2A2 (ATPase sarcoplasmic/endoplasmic reticulum Ca2+ transporting 2)
Diseases named in the same sentence as ATP2A2 in open-access papers (continued):
Sharing a sentence is not in itself a finding about the gene and the disease.
Right ventricular cardiomyopathy (1 paper, 2021). Right ventricular dysfunction (global or regional) with functional and morphological right ventricular abnormalities, with or without left ventricular disease. "Moreover, MYL4 detected by both bioinformatic and ML analysis, was already validated in a previous study, while ATP2A2 is reported to be associated to “arrhythmogenic right ventricular cardiomyopathy” pathway by KEGG." (PMID 34946895, 2021).
squamous cell tumors (1 paper, 2021). "Liu and colleagues showed that heterozygous mutant ATP2A2 mice develop late-onset squamous cell tumors in the gut and in the skin where the expression of SERCA2 protein is reduced due to haploinsufficient loss-of-function mutations." (PMID 33407740, 2021).
systolic heart failure (1 paper, 2025). Heart failure caused by abnormal myocardial contraction during systole leading to defective cardiac emptying. "SERCA2a, encoded by ATP2A2, mediates calcium reuptake in cardiomyocytes, and its dysfunction is a hallmark of systolic heart failure." (PMID 41007658, 2025).
ventricular dilatation (1 paper, 2022). "Thus, whole-heart Atp2a2 knockout led to reduced cardiac contractile functions and ventricular dilatation." (PMID 35433671, 2022).
cancer (22 papers, 2010 to 2025). A tumor composed of atypical neoplastic, often pleomorphic cells that invade other tissues. "Prior research has shown that ATP2A2 is associated with cancer risk." (PMID 37559135, 2023). "Near the CNV (chr19:3,266,850–3,271,865), there is an ATP2A2 gene (chr19:3,274,476–3,308,472), which is correlated with different cancer types." (PMID 28486430, 2017). "ATP2A1 expression negatively affected patient survival rates, especially in luminal, HER2-positive cancer and TNBC vs. normal controls, whereas ATP2A2 levels remained unaltered." (PMID 34684111, 2021). "Furthermore, ATP2A2 and SLC25A5 demonstrated a stronger positive correlation with NAAD+ in S-231 than in P-231 and confirmed the positive correlation between NAAD+ and the Ca2+ signaling pathway in stem-like cancer cells." (PMID 27391070, 2016).
tumor (19 papers, 2012 to 2026). "To understand how Notch1 loss alters tumor growth, we sequenced tumors from Notch1−/− epithelium, finding they share the same driver mutation, Atp2a2, (6/7 tumors), as the tumors from Notch1+/+ epithelium (17/17 tumors) 35,36." (PMID 36658434, 2023). "The ARRDC1 and ATP2A2 genes are primarily associated with macrophages, monocytes, follicular helper T cells, and NK cells, thereby reinforcing the link between immune infiltration and the tumor microenvironment." (PMID 41300841, 2025). "Toki and colleagues confirmed these initial observations and showed that the onset of ATP2A2-deficient tumor depends on the level of SERCA residual activity, suggesting that SERCA haploinsufficiency may predispose to multistage carcinogenesis by altering Ca2+ homeostasis." (PMID 33407740, 2021). "In the mouse oesophagus, NOTCH1 wild-type cells are more likely to contribute to tumours than NOTCH1 mutant cells; NOTCH1 loss reduced tumour size by slowing cell division and attenuating signalling downstream of mutant ATP2A2." (PMID 38172609, 2024). "ATP2A2 and ARID5B correlated with the GH change rate in the octreotide loading test, and WWC3, SERINC1, and ZFAND3 correlated with the tumor volume change rate after somatostatin analog treatment." (PMID 36435867, 2022). "Binding of STING with VDAC2, ATP2A2, and ATP1A1 was confirmed in both A498 and RCC10 tumor cells." (PMID 36445063, 2023). "ATP2A2 and ARID5B were identified as being correlated with the GH change rate in response to octreotide treatment, and WWC3, SERINC1, and ZFAND3 were identified as being correlated with the tumor volume change rate in response to SSA treatment." (PMID 36435867, 2022).
heart disease (13 papers, 2012 to 2023). "In addition, ATP2A2 is predicted to be highly intolerant to mutations in a number of other contexts including the cardiovascular system (EvoTol percentile score = 8.2 in adult heart tissue), suggesting an additional pathogenic role for this gene in cardiac disease, as previously reported." (PMID 25550428, 2015). "We therefore analyzed Atp2a2 heterozygous mice to determine whether SERCA2 haploinsufficiency can exacerbate specific heart disease conditions." (PMID 26064889, 2015). "Atp2a2 heterozygosity did not exacerbate the cardiac disease phenotype of DCM mice." (PMID 26064889, 2015).
infection (8 papers, 2009 to 2026). The state of being infected such as from the introduction of a foreign agent such as serum, vaccine, antigenic substance or organism. "Some of these, like ATG13 and ATXN3, are upregulated in VZV-infected cells, whereas, e.g., ATP2A2 is downregulated upon infection." (PMID 38025266, 2023). "In response to infection, aquaporin (AQP11) expression was reduced, whereas ATPase transporters (ATP2A2, ATP7A) expression were significantly elevated." (PMID 39703373, 2024).
psychiatric disorder (4 papers, 2017 to 2025). A disorder characterized by behavioral and/or psychological abnormalities, often accompanied by physical symptoms. "Thus, increased levels of extracellular DA in the NAc may explain a causal relationship between ATP2A2 and mental illness." (PMID 34104969, 2021).
skin disorder (4 papers, 2021 to 2025). Any deviation from the normal structure or function of the skin or subcutaneous tissue that is manifested by a characteristic set of symptoms and signs. "Moreover, we plan to follow the probands with ATP2C1 and ATP2A2 variants to see if interventions targeting their skin disorders will also ameliorate their IC/BPS symptoms." (PMID 36910591, 2023). "She did not present any skin disorder, suggesting psychiatric manifestations might be independent of skin pathology in patients with ATP2A2 haploinsufficiency." (PMID 34659328, 2021).
ATP2A2 also shares sentences with these, for which no sentence is quoted: type 2 diabetes (10 papers); Insulin resistance (8); Sepsis (8); diabetic cardiomyopathy (7); metabolic disorders (7); Arrhythmia (6); bipolar disorder (6); Glucose intolerance (6); myocardial infarction (6); Hyperglycemia (5); asthma (4); genetic disorder (4); myocardial ischemia (4); Ventricular arrhythmia (4); atherosclerosis (3); atrial fibrillation (3); cardiovascular diseases (3); depression (3); diabetic nephropathy (3); epilepsy (3); infarction (3); ischemia (3); lung carcinoma (3); mood disorder (3); ovarian carcinoma (3); Parkinson disease (3); Spinocerebellar ataxia (3); acute promyelocytic leukemia (2); adenoma (2); arrhythmogenic right ventricular cardiomyopathy (2).
A further 75 diseases each share a sentence with ATP2A2 in 2 papers or fewer.